TIMM17A (translocase of inner mitochondrial membrane 17A)
Description:
Essential component of the TIM23 complex, a complex that mediates the translocation of transit peptide-containing proteins across the mitochondrial inner membrane.
Synonyms: TIM17; TIM17A
Tractability: Antibody: UniProt predicts a signal peptide or a membrane-spanning region. PROTAC: ubiquitination databases record sites on it; its protein half-life has been measured.
Gene: Protein-coding gene on chromosome 1 (201,955,476 to 201,970,664, forward strand). Ensembl gene ENSG00000134375.
Subcellular location: Mitochondrion inner membrane
Subcellular location (Human Protein Atlas): Mitochondria; Nucleoplasm
Pathways (Reactome):
Metabolism of proteins: Mitochondrial protein degradation
Protein localization: Mitochondrial protein import
Gene Ontology:
Molecular function: protein transmembrane transporter activity
Biological process: intracellular protein transport; protein import into mitochondrial matrix
Cellular component: mitochondrial inner membrane; mitochondrion; TIM23 mitochondrial import inner membrane translocase complex
Genetic constraint (gnomAD): Loss-of-function variants: 11 observed, 19.14 expected, observed/expected ratio (o/e) 0.57, 90% interval 0.36 to 0.95. The upper end of that interval is the gene's LOEUF score, 0.95, which puts it in group 4 of 6, group 1 being the genes least tolerant of losing a copy. Missense variants: 178 observed, 190.63 expected, observed/expected ratio (o/e) 0.93, 90% interval 0.83 to 1.06. Synonymous variants: 70 observed, 66.48 expected, observed/expected ratio (o/e) 1.05, 90% interval 0.87 to 1.28.
Homologues: Orthologues: chimpanzee TIMM17A (99% identical), guinea pig TIMM17A (98% identical), pig TIMM17A (96% identical), mouse Timm17a (96% identical), macaque TIMM17A (95% identical), rat Timm17a (95% identical), zebrafish timm17a (87% identical), tropical clawed frog timm17a (82% identical), dog TIMM17A (81% identical), Drosophila melanogaster Tim17b (67% identical), Drosophila melanogaster Tim17b2 (59% identical), Drosophila melanogaster CG1724 (58% identical), and 5 more. Paralogues in human: TIMM17B (76% identical).
Diseases named in the same sentence as TIMM17A in open-access papers:
TIMM17A is named in the same sentence as 15 diseases in open-access papers, as found by Europe PMC text mining. Sharing a sentence is not in itself a finding about the gene and the disease. The quoted sentences say what the papers report.
breast carcinoma (5 papers, 2019 to 2024). "In conclusion, NEAT1-caused down-regulation of miR-133b promotes breast cancer metastasis through up-regulating TIMM17A, a target of miR-133b." (PMID 31344855, 2019). "Interestingly, recent research has highlighted the potential role of TIMM17A in breast cancer, where its expression is upregulated and associated with poor pathological and clinical outcomes." (PMID 38632467, 2024). "TIMM17A was found to promote breast cancer tumorigenesis and metastasis, and its high expression is associated with adverse pathological and clinical outcomes in human breast cancer." (PMID 31344855, 2019). "Moreover, the transcriptional upregulation of TIMM17A was implicated in breast cancer." (PMID 38837610, 2024). "Mechanistically, we found that mitochondrial protein translocase of inner mitochondrial membrane 17 homolog A (TIMM17A) could be a target of miR-133b, and miR-133b silencing caused TIMM17A up-regulation leading to the metastasis of breast cancer both in vitro and in vivo." (PMID 31344855, 2019). "Translocase of inner mitochondrial membrane 17A (TIMM17A) is overexpressed in breast cancer (BRCA), and upregulation can increase the aggressiveness of BRCA cells." (PMID 34421983, 2021). "Taken together, these results supported the role of miR-133b in promoting breast cancer cell metastasis in mice through suppressing TIMM17A expression." (PMID 31344855, 2019). "Both miR-133b knockdown and TIMM17A overexpression in breast cancer cells promoted cell migration and invasion both in vitro and in vivo." (PMID 31344855, 2019). "However, TIMM17A has been rarely studied in cancers, and only two studies suggested that high TIMM17A expression is associated with adverse pathological and clinical outcomes in human breast cancer, and facilitates migration and invasion of breast cancer cells." (PMID 31344855, 2019). "Collectively, these data demonstrated that miR-133b silencing promoted migration and invasion of breast cancer cells through targeting TIMM17A." (PMID 31344855, 2019). "We also investigated the role of miR-133b/TIMM17A in mediating breast cancer cells metastasis in the mouse model by using four types of modified MCF-7 cell lines." (PMID 31344855, 2019). "We also confirmed that lncRNA NEAT1 was up-regulated in breast cancer and inhibited the expression of miR-133b, and identified the mitochondrial protein translocase of inner mitochondrial membrane 17 homolog A (TIMM17A) that serves as the target of miR-133b." (PMID 31344855, 2019). "In summary, our findings reveal that miR-133b plays a critical role in breast cancer cell metastasis by targeting TIMM17A." (PMID 31344855, 2019). "Our data also revealed that TIMM17A was up-regulated in breast cancer, and its high expression predicted poor clinical outcome for breast cancer patients." (PMID 31344855, 2019). "The rescue experiments were performed by transfecting breast cancer cells with miR-133b mimics or inhibitor, and TIMM17A vector or siRNA." (PMID 31344855, 2019). "We measured TIMM17A protein levels in the breast cancer cells and normal breast cells, and found TIMM17A protein levels were higher in the breast cancer cells." (PMID 31344855, 2019). "Western blotting results showed TIMM17A protein levels were significantly increased in paired breast cancer tissues and adjacent normal tissues and TIMM17A protein levels were higher in all the breast cancer tissues than their adjacent normal tissues." (PMID 31344855, 2019). "Moreover, TIMM17A has been identified as a potential biomarker for breast cancer and has been found to promote the proliferation and migration of breast cancer cells." (PMID 38632467, 2024). "Such a specific behavior of TIMM17A in breast cancer made us question whether the transcription of other components of the TIM23 complex, especially TIMM17B, might be dysregulated in various cancers." (PMID 38837610, 2024). "The role of TIMM17A in breast cancer has been extensively studied." (PMID 38632467, 2024).
breast carcinoma (continued). "Type and frequency of TIMM17A neighbor gene alterations in breast carcinoma (cBioPortal)." (PMID 34421983, 2021). "We next focused on studying whether silencing of miR-133b facilitates breast cancer cell migration and invasion by up-regulating TIMM17A expression." (PMID 31344855, 2019). "In this study, we proposed that TIMM17A could serve as a target of miR-133b, and it was required for breast cancer cell migration and invasion both in vitro and in vivo." (PMID 31344855, 2019). "Our study firstly revealed that the NEAT1/miR-133b/TIMM17A axis was involved in breast cancer metastasis and might provide a potential target for breast cancer therapy." (PMID 31344855, 2019). "Finally, we investigated the role of miR-133b in mediating breast cancer cells metastasis in the mouse model by targeting TIMM17A." (PMID 31344855, 2019). "Each of the three players in NEAT1/miR-133b/TIMM17A axis may become a novel therapeutic target for the treatment of breast cancer, which is of crucial significance for the clinical prevention and diagnosis of breast cancer." (PMID 31344855, 2019). "Taken together, these results indicated that TIMM17A is a direct target of miR-133b in breast cancer and might be correlated with poor outcome in breast cancer patients." (PMID 31344855, 2019). "By searching StarBase public database, we found TIMM17A mRNA levels were remarkably higher in 1104 breast cancer tissues compared to 113 normal breast tissues, and its high expression predicts a poor prognosis in breast cancer patients (n = 2519, p < 0.005) using the Kaplan Meier Plotter." (PMID 31344855, 2019). "Moreover, we confirmed miR-133b suppressed breast cancer metastasis through targeting TIMM17A in the mouse xenograft model." (PMID 31344855, 2019). "By measuring the expression levels of TIMM17A in breast cancer tissues and adjacent normal tissues, we found TIMM17A levels were up-regulated in 87.5% (35 of 40 paired) of breast cancer tissues compared with adjacent normal tissues and negatively correlated with miR-133b levels." (PMID 31344855, 2019). "Therefore, we investigated whether the miR-133b expression is inversely correlated with TIMM17A expression in breast cancer cells and clinical specimens." (PMID 31344855, 2019).
lung carcinoma (3 papers, 2012 to 2024). "A first interesting observation about these genes is that many of them have been positively implicated in breast and/or lung cancer progression and resistance to therapy: AURKA, CAV2, RAB27A, RAD51, TIMELESS, TIMM17A." (PMID 22347440, 2012). "Hsa-miR-372 is already a potential marker of lung cancer, and regulates an ATPase family member ATAD2, a translocase of inner mitochondrial membrane 17 (TIMM17A) and the transcription factor E2F5." (PMID 24866763, 2014).
fibrolamellar hepatocellular carcinoma (1 paper, 2024). A distinctive type of liver cell carcinoma that arises in non-cirrhotic livers and is seen predominantly in young patients. "In fibrolamellar hepatocellular carcinoma (FLC), including primary and metastatic tumors, TIMM17A is frequently overexpressed on the 1q chromosome, suggesting its potential role as an oncogene in this rare subtype of liver cancer." (PMID 38632467, 2024).
lymph node metastasis (1 paper, 2024). "Our results indicate that TIMM17A is significantly upregulated in LUAD tissues, correlating with clinical staging, lymph node metastasis, overall survival, and progression-free survival, thereby establishing it as a critical independent prognostic factor." (PMID 38632467, 2024). "Significantly, TIMM17A levels were higher in patients with lymph node metastasis compared to those without." (PMID 38632467, 2024).
triple-negative breast carcinoma (1 paper, 2024). An invasive breast carcinoma which is negative for expression of estrogen receptor (ER), progesterone receptor (PR), and human epidermal growth factor receptor 2 (HER2). "In invasive and triple-negative breast cancer (TNBC), TIMM17A has been identified as a key target gene of miR-24-2 and miR-133b, with its low expression associated with improved survival, indicating diagnostic and therapeutic potential." (PMID 38632467, 2024).
cancer (6 papers, 2019 to 2024). A tumor composed of atypical neoplastic, often pleomorphic cells that invade other tissues. "TIMM17A has been increasingly recognized as a key player in tumorigenesis, with its aberrant expression linked to the progression and prognosis of various cancers." (PMID 38632467, 2024). "Among some genes associated with disease and immunity, DOK2 and TIMM17A are related to cancer, LMODI is linked to hypoperistalsis, MAVS is essential for virus-activated signaling pathways, and DOCK8 is linked to humoral immunity." (PMID 36139261, 2022). "Additionally, the PI3K/AKT signaling pathway, which is implicated in tumorigenesis and cancer progression, has been found to be involved in the action of TIMM17A and its role in breast cancer." (PMID 38632467, 2024). "The proportions of cells in S-phases were reduced by TIMM17A knockdown, suggesting that TIMM17A serves to enhance cancer cell proliferation." (PMID 34421983, 2021). "Our research commenced with an examination of TIMM17A expression levels in LUAD, utilizing data from the Cancer Genome Atlas (TCGA), Clinical Proteomic Tumor Analysis Consortium (CPTAC), and Human Protein Atlas (HPA) to analyze both mRNA and protein expression profiles." (PMID 38632467, 2024). "Our analysis showed that an increase in transcriptional level in cancer is not a distinctive feature of the TIM23 complex or TIMM17A alone, but there is a general increase in transcript numbers of mitochondrial proteins." (PMID 38837610, 2024).
tumor (5 papers, 2016 to 2025). "Expression levels of TIMM17A were compared between normal and tumor tissues from the OncomineTM database, and the association with patient survival was analyzed using Kaplan–Meier Plotter." (PMID 34421983, 2021). "Mitochondrial protein TIMM17A contributes to a pre-protein import complex, which is essential for mitochondrial function, and mitochondrial dysfunction is considered as a hallmark of tumor pathogenesis." (PMID 31344855, 2019). "Furthermore, in our analysis of tumor grade, TIMM17A protein expression substantially increased with advancing grade." (PMID 38632467, 2024). "While there was no marked difference in TIMM17A expression across different tumor stages and N-stage, a notable increase in TIMM17A expression was observed across LUAD Stage I-IV." (PMID 38632467, 2024). "In mice injected with TIMM17A-overexpressing or miR-133b-knocked down MDA-MB-231 cells, tumors with clear boundaries (arrows), higher quantities and size were found in the lungs, while only less and smaller tumor masses were scattered in the lungs of miR-133b over-expression group." (PMID 31344855, 2019).
TIMM17A also shares sentences with these, for which no sentence is quoted: 3-methylglutaconic aciduria type 9 (1 paper); breast tumor (1); colorectal cancer (1); cystic fibrosis (1); ductal carcinoma in situ (1); invasive ductal carcinoma (1); lung adenocarcinoma (1); metastatic tumors (1).